CD28 (CD28 molecule)
Diseases named in the same sentence as CD28 in open-access papers (continued):
Sharing a sentence is not in itself a finding about the gene and the disease.
periodontitis (7 papers, 2015 to 2024). An acute or chronic inflammatory process that affects the tissues that surround and support the teeth. "Finally, we discuss the existing literature that allows us to suggest the potential pathogenic role of senescent CD4+CD28− T lymphocytes in periodontitis." (PMID 35269683, 2022). "Genetic polymorphisms of pro‐inflammatory mediators MMP3, CD28, and VDR seem to link to initial periodontitis." (PMID 29744169, 2016). "Similar to results obtained from defect site blood, CD8+/CD28+ was found to be significantly higher in both periodontitis group than healthy subjects in systemic blood (p < 0.05)." (PMID 25788457, 2015). "The two-way relationship between T2DM and chronic periodontitis, with senescent CD4+CD28- T cells potentially serving as mediators, is a good example." (PMID 38586464, 2024).
sarcoidosis (7 papers, 2012 to 2024). Sarcoidosis is a multisystemic disorder of unknown cause characterized by the formation of immune granulomas in involved organs. "Of the 31 TCR/JS/CCR-gene signature genes, 8/31 genes were cited in the sarcoidosis literature with CD28, IFNG, IL7R, AKT3, IL2RA, IL2RB, and STAT4 demonstrating a robust relationship with these terms." (PMID 22984568, 2012). "Compared with conventional CD4+ T cell lines that were co-cultured with anti-CD3 and anti-CD28 antibodies, polarized Th17 cells from both a BD patient, a sarcoidosis patient, and a healthy donor produced large amounts of IL-17, particularly BD T cells, as determined by ELISA." (PMID 22546542, 2012). "Whereas proportions of Tregs expressing CD28 were high and unaltered, the fractions of CTLA4+ and PD-1+Tregs were increased in sarcoidosis, compared with HCs." (PMID 38715030, 2024). "Further CD8 T cell phenotyping revealed a similar distribution of effector memory subsets according to their CD27 and CD28 expression compared to patients with sarcoidosis (data not shown)." (PMID 33613543, 2020). "Additional pathways that were different between progressive and non-progressive sarcoidosis in the BALF included CD28 signaling and PFKFB4 signaling." (PMID 32764642, 2020). "Additionally, CD28 controls differentiation of Tregs from naïve CD4 T cells, providing novel mechanisms that may explain progression or remission of sarcoidosis." (PMID 32764642, 2020). "CD8+ T cells were isolated from peripheral blood of healthy controls or Sarcoidosis patients and stimulated by plate-bound anti-CD3 and anti-CD28 antibodies with or without IL-17 for 3 days." (PMID 24885153, 2014).
ulcerative colitis (7 papers, 2020 to 2026). An inflammatory bowel disease involving the mucosal surface of the large intestine and rectum. "CIP-3 also suppresses cytokine production across independent healthy donors and patient-derived PBMCs from individuals with ulcerative colitis with efficacy comparable to a benchmark anti-CD28 biologic." (PMID 42216689, 2026). "On the other hand, CD+4 T cells derived from healthy control or ulcerative colitis patients were activated by anti-CD3 and anti-CD28 antibodies along with vehicle or 50 nM HHT for 72 hours." (PMID 36211988, 2022).
unstable angina (7 papers, 2015 to 2024). "Also peripheral blood mononuclear cells cocultured with TNF-α showed downregulation of the CD28 costimulatory receptor, and high levels of TNF-α are associated with higher levels of CD4+CD28− T cells in patients with unstable angina, supporting the findings of the in vitro studies." (PMID 25834833, 2015). "Specifically, high proportions of CD4+ CD28- T cells have been reported in individuals with unstable angina, within unstable plaques, and in persons with recurrent coronary events." (PMID 36865544, 2023). "An increased risk for angina pectoris, myocardial infarction, and cardiac death has also been described for patients with rheumatoid vasculitis and patients with chronic kidney disease depending on their level of CD4+CD28− T cells." (PMID 25834833, 2015). "Reportedly, plaques in unstable angina patients present clonally expanded peripheral blood CD4 T cells lacking CD28 expression (CD4+CD28null), which are also increased in patients with RA." (PMID 38627782, 2024). "In ATS plaques that form in unstable angina patients, CD4+ cells without the co-stimulatory receptor CD28 (CD4+ CD28null T cells) are formed and expanded in the peripheral blood of these patients as well as a subset of RA patients." (PMID 35206926, 2022).
Alzheimer disease (6 papers, 2012 to 2025). A progressive, neurodegenerative disease characterized by loss of function and death of nerve cells in several areas of the brain leading to loss of cognitive function such as memory and language. "The expansion of CD28- T cells has been also reported in neuropsychiatric disorders associated with cognitive impairment, including bipolar disorder, early-life stress, and Alzheimer’s disease." (PMID 32190092, 2020). "A decrease in Cd28+ Th cells has been observed in patients with Alzheimer’s disease and Parkinson’s disease, which correlates with reduced Tregs and exacerbated neuroinflammation." (PMID 40072375, 2025). "PU.1low CD28-expressing microglia may act as suppressive cells in Alzheimer’s disease, mitigating its progression by reducing neuroinflammation and amyloid plaque load, indicating potential immunotherapeutic approaches for treatment." (PMID 41193812, 2025). "Indeed, patients with mild cognitive impairment or Alzheimer’s disease had increased expansion of late-differentiated T cells (CD28-)." (PMID 32190092, 2020).
co-infection (6 papers, 2015 to 2025). "CMV co-infection was significantly associated with lower percentages of naïve CD8+CD62L+CD45RA+ and CD8+CD95-CD28+ T-cells and higher percentage of terminally differentiated CD8+CD95+CD28- T-cells both at baseline and in their longitudinal trends." (PMID 25794163, 2015). "Despite the inhibitory effect that HIV infection has on T-cell differentiation, HIV-TB co-infection presents with an accelerated decline in CD27 and CD28." (PMID 38903242, 2024). "Co-infection of HIV with M. tuberculosis appears to expedite the downregulation of CD27 and CD28 compared to HIV infection alone." (PMID 38903242, 2024). "We conclude that longitudinal trends in percentages of CD8+CD62L+CD45RA+ (naïve), CD8+CD95-CD28+ (naïve), and CD8+CD95+CD28- (terminally differentiated) T-cells, following switch in cART, were significantly adversely affected by CMV co-infection in this cohort of PHIV+ children." (PMID 25794163, 2015).
Crohn disease (6 papers, 2015 to 2024). A gastrointestinal disorder characterized by chronic inflammation involving all layers of the intestinal wall, noncaseating granulomas affecting the intestinal wall and regional lymph nodes, and transmural fibrosis. "We found that CD28 expression on CD39+ secreting CD4 Treg cells in the peripheral blood was negatively associated with the risk of Crohn disease." (PMID 39058862, 2024). "Recent research has revealed association of CD28 downregulation with the activity index of Crohn’s disease." (PMID 33585004, 2020). "Moreover, CD27 and CD28 downregulation on CD4+ T cells has been previously associated with other intestinal inflammatory diseases such as Crohn’s Disease." (PMID 38239362, 2023). "In fact, the larger number of memory T cells accompanied by downregulated CD28 expression is introduced as a sign of active Crohn’s disease." (PMID 33585004, 2020). "Among the 81 queried DEGs related to Crohn’s disease, 7 genes (IL-7, GATA3, CD28, CD5, TXN, ETS-1, and CCR7) were introduced as dysregulated genes." (PMID 33585004, 2020). "Through network analysis, we can introduce IL-7, GATA3, TXN, ETS-1, CCR7, CD28, and CD5 as Crohn’s disease-related critical genes and possible biomarker panel." (PMID 33585004, 2020). "In immunologically mediated diseases such as Crohn's disease, CD8+ T-cell activation can be boosted by activated antigen-presenting cells and this occurs, at least in part, via elicitation of CD3/CD28 signalling." (PMID 26549640, 2015). "We note that polyclonal activation of CD8+ T cells (by anti-CD3/CD28 antibodies) boosts CD39 expression on these cells, consistent with the increased frequency of CD39+CD8+ T cells seen in the blood and inflamed tissues of patients with active Crohn's disease." (PMID 26549640, 2015).
Immunodeficiency (6 papers, 2004 to 2018). Failure of the immune system to protect the body adequately from infection, due to the absence or insufficiency of some component process or substance. "Recently, two groups have reported that spontaneous gain of function mutations in PI3K resulted in profound immunodeficiency, as these T cells were unable to mount an efficient immune response to cross-linked anti-CD3/CD28 stimulation." (PMID 26440416, 2015). "This was associated with an intrinsic defect in anti-CD3/CD28 T cell proliferation that was partially IFN dependent and correlates with our phenotypic observation of reduced anti-CD3/CD8 stimulated cell proliferation and immunodeficiency in our patient." (PMID 30038614, 2018). "The abnormal kinetics and levels of CD28 and CD152 expression on T cells in B-CLL may lead to a state of hyporesponsiveness or anergy and could be one of the mechanisms of immune deficiency in this disease." (PMID 15138491, 2004). "ICOS is a CD28 and CTLA-4 cell-surface receptor family protein, which functions in immunodeficiency biological processes." (PMID 26457008, 2015). "In summary, the dysregulated expression and kinetics of the costimulatory CD28 and downregulatory CD152 molecules on PB T cells of patients with B-CLL may likely have a considerable impact on the biology of T-cell responses and could be one of the mechanisms of immune deficiency in this disease." (PMID 15138491, 2004).
lung adenocarcinoma (6 papers, 2020 to 2024). A carcinoma that arises from the lung and is characterized by the presence of malignant glandular epithelial cells. "Furthermore, in lung adenocarcinoma, patients with high CD28 expression have lower disease-free survival (DFS)." (PMID 35874743, 2022). "By interrogating the TCGA dataset of patients with lung adenocarcinoma (LUAD) and metastatic NSCLC treated with atezolizumab, we found signatures of heterogeneous TRM and "pre-exhausted" long-lived effector memory CD8+ T cells associated with improved response to ICB only in the presence of CD28." (PMID 37898752, 2023). "We found that the expression of CD28, CD80, andCD86 was markedly reduced, suggesting that PSMB6 may decrease their expression to reduce the binding between CD80/CD86 and CD28, ultimately leading to immune evasion in lung adenocarcinoma cells." (PMID 39507618, 2024).
myocardial infarction (6 papers, 2010 to 2024). Gross necrosis of the myocardium, as a result of interruption of the blood supply to the area, as in coronary thrombosis. "The blockade of CD28 signals also exacerbated left ventricular remodeling and increased cardiac rupture after myocardial infarction by prolonging the inflammatory period, which caused a reduction in collagen fibers in infarct scars." (PMID 31565151, 2019). "Animals were randomly allocated to treatment with a single dose of the ligand binding inhibiting anti-CD28 mAb E18 or a mAb of the same isotpye (IgG2b), but irrelevant specificity, on day two after myocardial infarction (MI)." (PMID 32298302, 2020). "One of the CD28% High subjects died from a myocardial infarction, and another had fatal pulmonary thromboemboli." (PMID 20126467, 2010). "We showed previously that stimulation of CD4+ Foxp3+ regulatory T-cells by superagonistic anti-CD28 monoclonal antibodies (mAb) improves myocardial healing after experimental myocardial infarction (MI)." (PMID 32298302, 2020).
osteosarcoma (6 papers, 2014 to 2024). A usually aggressive malignant bone-forming mesenchymal neoplasm, predominantly affecting adolescents and young adults. "In support of this result, a biomarker experiment study showed that the CD86/CD28 stimulatory pathway associated with activated memory CD4 T cells was dominant in osteosarcoma patients with a good prognosis." (PMID 39081321, 2024). "In osteosarcoma, CD28 expression is significantly associated with activated memory CD4 T-cells." (PMID 35463956, 2022). "B7-H3 CAR T cells were more cytotoxic than HER2 CAR T cells toward canine osteosarcoma spheroids, but cytotoxicity was similar for the constructs incorporating CD28 or 4-1BB signaling domains." (PMID 36876006, 2023). "In this study, CD86 expression was significantly correlated with CTLA4 and CD28 expression in osteosarcoma." (PMID 35463956, 2022). "In summary, blocking CD86/CTLA4 signaling and promoting CD86/CD28 signaling are potential strategies for osteosarcoma immunotherapy." (PMID 35463956, 2022). "Combining these results, we deduced that the CD86/CD28 stimulatory pathway was dominant in osteosarcoma patients with a good prognosis." (PMID 35463956, 2022). "Using a threshold of >5-fold T cell expansion during stimulation with CD3/CD28 beads as a marker for “healthy” effector function, we demonstrate that 57% of osteosarcoma samples in this study had >5-fold T cell expansion, compared to 0% of Ewing sarcoma." (PMID 35938052, 2021). "Thus, blocking CD86/CTLA4 signaling and promoting CD86/CD28 signaling are potential strategies for osteosarcoma immunotherapy." (PMID 35463956, 2022). "Thus, decreased expression of CD28 could lead to disability of the activation function of T cells and help to shape an immunosuppressive phenotype for osteosarcoma progression." (PMID 39081321, 2024). "Moreover, CD86 expression depended on its receptors, CTLA4 and CD28, in osteosarcoma." (PMID 35463956, 2022). "A HER2 CAR T cell therapy with canine CD28 and CD3ζ signaling domains secreted IFNγ and was cytotoxic against HER2+ osteosarcoma and breast cancer target cell lines in vitro." (PMID 36876006, 2023).
renal cell carcinoma (6 papers, 2014 to 2024). "Similarly, upregulation of SLC2A3 could enhance CD28 costimulation reprogrammed renal cell carcinoma CD8+ TIL metabolism, which is antagonized by the inhibitory and checkpoint immunotherapy receptors CTLA4 and PD-1." (PMID 36247875, 2022). "As an exception, renal cell carcinoma (RCC) CD8+ tumor-infiltrating lymphocytes (TILs) specifically upregulate GLUT3 in response to CD28 co-stimulation." (PMID 33086598, 2020). "Moreover, in another study, CD8+ TILs from renal cell carcinoma showed decreased uptake of glucose and altered mitochondria, and the authors demonstrated that in vitro CD28 costimulation could rescue effector function by increasing glycolysis and consequently mitochondrial potential and mass." (PMID 36203587, 2022). "Binding to murine CCR4 was additionally confirmed in the flow cytometry experiments using CCR4+ murine renal cell carcinoma cell line Renca and the mouse splenocytes, which express CCR4 upon activation via CD3 and CD28." (PMID 25080123, 2014).
vasculitis (6 papers, 2012 to 2025). "A 6-month course of valaciclovir therapy has been shown to mediate a 28% reduction the proportion of CD4+CD28- T cells in patients undergoing immunosuppressive therapy for vasculitis and was associated with enhanced immune response to pneumococcal vaccination." (PMID 41460874, 2025). "In this respect, the use of Valacyclovir as anti-CMV treatment in patients with Antineutrophil Cytoplasmic Antibody (ANCA)-Associated Vasculitis was shown not only to suppress CMV reactivation but was also associated with a reduction of the CD4+CD28− T-cell frequency." (PMID 34576140, 2021). "In Takayasu’s arteritis (TAK), another large vasculitis, the active patients had higher mRNA levels of CD28 than the inactive patients." (PMID 37090741, 2023).
celiac disease (5 papers, 2009 to 2023). An autoimmune genetic disorder with an unknown pattern of inheritance that primarily affects the digestive tract. "DEXSeq found evidence of differential exon usage in our anti-CD3/CD28 stimulated samples at 4 genes that have been genetically associated with Coeliac disease." (PMID 26444573, 2015). "We therefore characterised genome-wide differences in transcription between individuals with coeliac disease and unaffected controls in resting cells and cells activated using two different stimulations (anti-CD3/CD28 and PMA)." (PMID 26444573, 2015).
ischemic stroke (5 papers, 2014 to 2022). A stroke disorder caused by obstruction of blood flow to the brain, due to thrombotic (local blood clot formation) or embolic (due to a blood clot or other material traveling from another site) event. "This imbalance might contribute the pathology since it was shown that CD28 superagonist reduced brain damage after ischemic stroke in mice by amplification of Treg cells." (PMID 34427746, 2022). "We hypothesized that CD4+ cells and, in particular, the CD28 null cell subset could show a different degree of peripheral percentage in subjects with acute ischemic stroke in relation to clinical subtype and severity of ischemic stroke." (PMID 25997053, 2015). "Only 2 studies previously analyzed peripheral frequency of CD28 null cells in subjects with acute ischemic stroke but, to our knowledge, peripheral frequency of CD28 null cells in each TOAST subtype of ischemic stroke has never been evaluated." (PMID 25997053, 2015). "Thus, it appeared as though the molecules of the CD80/CD28, CTLA-4, and the PD-1/PD-L pathway are more critical than others in ischemic stroke." (PMID 25157219, 2014).
kidney transplant (5 papers, 2013 to 2021). A surgical procedure in which one or both kidneys from a donor are implanted into a recipient. "The high-affinity CTLA4-Ig, belatacept, currently approved for use in kidney transplant recipients inhibits CD28 costimulation, a critical pathway for Tconv cell activation as well as Treg cell development and homeostasis." (PMID 29973932, 2018). "Clinical trials investigating B7/CD28 blockade (LEA29Y, Belatacept) in kidney transplant recipients have proven that the replacement of toxic CNI use is feasible in selected populations." (PMID 23326509, 2013). "In stable long-term kidney transplant recipients, CD28-negative T cells have been recognized among other CD8-positive cells that correlate with allograft dysfunction." (PMID 30729139, 2019). "In contrast to TAC-based treatment, BELA-based immunosuppression does not inhibit key T cell activation pathways, despite the expression of CD28, which may contribute to the high rejection incidence observed among BELA-treated kidney transplant recipients." (PMID 29123208, 2017).
mantle cell lymphoma (5 papers, 2021 to 2024). Mantle cell lymphoma is a rare form of malignant non-Hodgkin lymphoma affecting B lymphocytes in the lymph nodes in a region called the ``mantle zone''. "We have compared the CD107a expression upon cellular stimulation by CD19 expressing JeKo-1 mantle cell lymphoma cell line (JeKo-1 WT) with Artificial Targets loaded with anti-FMC63 and anti-CD28 antibodies." (PMID 38433827, 2024). "Several studies have explored the clinical application of 4-1BB G3 CAR-T cells, with a small trial in four relapsed indolent B cell or mantle cell lymphoma (MCL) patients to test the safety of CD20-targeting CD28 and 4-1BB G3 CAR-T cells that were already reported in 2012." (PMID 35053463, 2022). "Furthermore, brexucabtagene autoleucel (KTE-X19), another CD3ζ/CD28-based CD19-specific CAR-T cell, is specified for mantle cell lymphoma (MCL) therapy." (PMID 34321099, 2021).